MSR1 (macrophage scavenger receptor 1)
Diseases named in the same sentence as MSR1 in open-access papers (continued):
Sharing a sentence is not in itself a finding about the gene and the disease.
leprosy (2 papers, 2019 to 2021). Leprosy is a chronic infectious disease affecting primarily the skin and peripheral nervous system. "When comparing leprosy patients to HHC, 16 genes showed significantly different expression for leprosy patients (increased: FCGR1A, IL6, IL15, LRKK2, MBP, MSR1, PACRGv1, TLR1, TLR4; decreased: CAMTA, CD3E, CTLA4, CXCL13, GATA3, LAG3, TFGB)." (PMID 31784594, 2019). "Whilst most of the genes overlap between the two comparisons, some genes discriminate leprosy patients from HHC exclusively (MBP, MSR1, TLR1, CAMTA, CXCL13 and TFGB)." (PMID 31784594, 2019). "A qPCR performed to evaluate pro- and anti-inflammatory related gene expression in skin lesions of leprosy patients revealed that pro-inflammatory genes STAT1, TNF, IFNG, IL15 and CSF2 are increased in PB cells, whereas anti-inflammatory MSR1 and PPARG genes are increased in MB cells." (PMID 34354699, 2021). "Importantly, whilst most of these genes were also differently expressed in leprosy patients compared to EC, MBP, MSR1, TLR1, CAMTA, CXCL13 and TFGB were differentially expressed in leprosy patients exclusively when compared to HHC." (PMID 31784594, 2019).
neuroblastoma (2 papers, 2021 to 2022). Neuroblastoma (NB) is the most common solid, extracranial childhood tumor. "Because the protective effects of MSR1 in nematode models of neurodegenerative pathology are paralleled by similarly positive results in cultured human neuroblastoma cells, GFAP and AD-associated kinases hold promise as novel targets for drug interventions to ameliorate AD-like neuropathies." (PMID 35890250, 2022). "MSR1 and MSR2 were initially tested for in vivo efficacy in SH-SY5Y-APPSw neuroblastoma cells; aggregation in this model was especially well suppressed by MSR1." (PMID 35890250, 2022).
prion disease (2 papers, 2021 to 2022). A transmissible disease that is caused by a protein that is able to induce abnormal folding of normal cellular proteins, leading to characteristic spongiform brain changes, which are associated with neuronal loss without an inflammatory response. "We first determined the Msr1 expression in a mouse model of prion disease and found Msr1 expression was significantly increased in prion-infected mouse brain." (PMID 33758958, 2021). "We observed that all Msr1+/+, Msr1+/-, and Msr1-/- mice succumbed to prion disease at a similar progression rate (median survival: 179 dpi for Msr1+/+ mice (n = 17), 186 dpi for Msr1+/-(n = 25) and 183.5 dpi for Msr1-/- mice (n = 14), p = 0.99)." (PMID 33758958, 2021). "To assess the function of Msr1 in prion pathogenesis, we next tested whether Msr1 ablation could affect prion disease progression and alter prion-mediated lesion pattern in mouse brains." (PMID 33758958, 2021). "We performed prion infection experiments with an appropriate number of animals (n=14~25 mice per group) and conclude, with a high degree of confidence, that Msr1 deficiency did not overtly affect progression of prion disease." (PMID 33758958, 2021). "The varied temporal pattern and magnitude of changes of Msr1 expression between prion disease and AD may explain its differential functions in these diseases." (PMID 33758958, 2021). "Together, these results indicate that Msr1 functions differently in AD and prion diseases." (PMID 33758958, 2021). "However, Msr1 deficiency did not change prion disease progression or lesion patterns." (PMID 33758958, 2021).
rheumatoid arthritis (2 papers, 2014 to 2022). A chronic, systemic autoimmune disorder characterized by inflammation in the synovial membranes and articular surfaces. "MSR1 has been investigated for its use as a biomarker and the pathological role it plays in rheumatoid arthritis (RA), a highly debilitating chronic autoimmune disease." (PMID 36325338, 2022). "Serum from rheumatoid arthritis patients (but not from healthy subjects) increased mRNA expression of the Msr1 gene in macrophages." (PMID 24505471, 2014).
thyroid cancer (2 papers, 2024 to 2026). "MR analysis confirmed MERTK and MSR1 as genetic risk factors for thyroid cancer progression, whereas TNFSF12 exhibited protective effects." (PMID 41930700, 2026).
acute myocardial infarction (1 paper, 2012). Necrosis of the myocardium, as a result of interruption of the blood supply to the area. "Some findings also suggest that the level of MSR1 gene expression increases only during the monocyte to macrophages differentiation, however the results of our study showed that it may be increased already in circulating monocytes, particularly in patients after acute myocardial infarction." (PMID 22763563, 2012).
adult-onset Still disease (1 paper, 2022). A rare inflammatory multisystem disorder characterized clinically by fever of unknown origin, arthralgia or arthritis, hyperleucocytosis, and typical skin rash. "The relevance of the animal model is underscored by the observation that enhanced NET formation, increased Msr1 expression and signalling on neutrophil leukocytes are also characteristic to adult-onset Still’s disease (AOSD), a typical hyperferritinemic syndrome." (PMID 36357401, 2022).
aneurysm (1 paper, 2023). Bulging or ballooning in an area of an artery secondary to arterial wall weakening. "Several human and animal studies endorse the upregulation and involvement of MSR1 in developing aneurysms." (PMID 36515067, 2023).
brain ischemia (1 paper, 2021). Diminished or absent blood supply to the brain caused by obstruction (thrombosis or embolism) of an artery resulting in neurologic damage. "We found that CD21, a newly synthesized neuroprotectant, ameliorated tPA-induced HT in brain ischemia by accelerating Prx1 clearance in an MSR1-dependent manner." (PMID 34162400, 2021). "Neuroinflammation that is stimulated by DAMPs (e.g., HMGB1 and Prxs) after brain ischemia was shown to be negatively regulated by MSR1, which conferred potent neuroprotection within a 24-h therapeutic time window in mice that were subjected to transient middle cerebral artery occlusion (tMCAO)." (PMID 34162400, 2021).
Cryptococcal meningitis (1 paper, 2023). Meningeal inflammation produced by cryptococcus neoformans, an encapsulated yeast that tends to infect individuals with acquired immunodeficiency syndrome and other immunocompromised states. "In addition, it may also be relevant to explore the effect of MSR1 polymorphisms on susceptibility to cryptococcal meningitis." (PMID 37580395, 2023).
Fulminant hepatitis (1 paper, 2022). Acute hepatitis complicated by acute liver failure with hepatic encephalopathy occurring less than 8 weeks after the onset of jaundice. "It has been reported that Msr1 promotes fulminant hepatitis by enhancing NETs22." (PMID 36357401, 2022). "In a murine model of fulminant hepatitis, Msr1 acts as an inflammatory accelerator through activating neutrophils and promoting the release of NETs, supporting the important pathogenetic role of Msr1 in neutrophilic inflammation." (PMID 36357401, 2022).
fungal infection (1 paper, 2023). "Our discovery of TLR/MSR1 crosstalk in the context of a fungal infection therefore suggests that TLR-SR crosstalk as a regulator of phagocytosis and cytokine expression is a general phenomenon of host-pathogen interactions." (PMID 37580395, 2023).
hereditary cancer (1 paper, 2018). Malignant neoplasms occurring in families at a rate greater than that expected by chance and caused by germline mutations in a specific gene. "A meta-analysis of eight studies that evaluated common MSR1 mutations and sequence variants, stratified by race, and sporadic or hereditary cancer concluded that the MSR1 gene does not independently confer a major risk to CaP but may confer a moderate risk to CaP, especially in black men." (PMID 29690565, 2018).
Hydrocephalus (1 paper, 2023). Hydrocephalus is an active distension of the ventricular system of the brain resulting from inadequate passage of CSF from its point of production within the cerebral ventricles to its point of absorption into the systemic circulation. "In conclusion, activation of the RARα attenuated CSF hypersecretion to inhibit hydrocephalus development via regulating the MAFB/MSR1 pathway." (PMID 36768908, 2023). "Firstly, we did not investigate the function of direct activation or inhibition of MSR1 in hydrocephalus." (PMID 36768908, 2023). "Therefore, we postulated that RARα receptor stimulation decreased CSF secretion via regulating inflammation in hydrocephalus by promoting the MAFB/MSR1 pathway." (PMID 36768908, 2023). "In this study, we confirmed that RARα might affect the occurrence and development of hydrocephalus through MSR1-mediated neuroinflammation." (PMID 36768908, 2023). "Importantly, the mechanism of RARα on hydrocephalus was associated with MAFB, MSR1, and neuroinflammation." (PMID 36768908, 2023). "Taken together, the current outcomes demonstrated that activation of the RARα attenuated CSF hypersecretion to inhibit hydrocephalus development, at least in part through the MAFB/MSR1 pathway." (PMID 36768908, 2023).
hyperferritinemia (1 paper, 2026). "Type I interferon signalling and neutrophil extracellular trap formation drive inflammation, while hyperferritinemia actively perpetuates disease through Msr1-mediated signaling." (PMID 41627555, 2026).
Hypertension (1 paper, 2022). The presence of chronic increased pressure in the systemic arterial system. "The expression of the MSR1 gene in atherosclerotic vessels increases the accumulation of fatty acids and lipoproteins in the blood, which in turn causes hypertension and ultimately damages the basement membrane of arteries." (PMID 35205232, 2022). "Furthermore, MSR1 is considered a potential marker in hypertension, in addition to other traditional risk factors." (PMID 35205232, 2022). "Here, we found the significant association of ADM, EDN1, ANGPTL4, USP8, NFIL3, MSR1, and CEBPD genes with hypertension." (PMID 35205232, 2022). "ADM, EDN1, ANGPTL4, NFIL3, MSR1, CEBPD, and USP8, based on their FDR values (<0.05, p-values (≤0.05)), were the top DEGs for hypertension." (PMID 35205232, 2022). "From 50 DEGs, we ranked 7 hypertension-related genes (p-value < 0.05): ADM, ANGPTL4, USP8, EDN, NFIL3, MSR1, and CEBPD." (PMID 35205232, 2022). "We observed that macrophage scavenger receptor 1 (MSR1) and CEBPD are downregulated in hypertension cases compared to control." (PMID 35205232, 2022).
infarction (1 paper, 2022). A localised pathological necrosis of tissue resulting from obstruction of the blood supply usually by a thrombus, an embolus, or vascular torsion. "MSR1 inhibits TNFs by promoting the expression of IL-10αexpression to regulate immunity, which is beneficial to the stability and regression of AS and myocardial repair after infarction." (PMID 36064568, 2022).
iron overloaded diseases (1 paper, 2012). "Based on our data, we can suggest the survey of MSR-1 effect on iron overloaded diseases in animal models and also survey of mechanism of clearance and immunity system response to MSR-1." (PMID 23066493, 2012).
morbid obesity (1 paper, 2021). An excess of body weight, normally defined as an individual with a body mass index greater than 35 or a body weight greater than one hundred percent of ideal body weight. "Regarding MSR1, we found a higher expression in patients with morbid obesity, an increase in hypoxia and a positive correlation with HIF-1α." (PMID 34829944, 2021).
neoplastic syndrome (1 paper, 2018). A broad classification for disorders in which the development of neoplasms typically occur in association with a characteristic set of signs or symptoms. "Furthermore, analysis of genes associated with risk of other inherited neoplastic syndromes different to HBOC identified heterozygous pathogenic variants for MSR1 (4%, 2/52), LIG4 (4%, 2/52) and PDE11A (6%, 3/52) in the affected women in both groups." (PMID 30262796, 2018).
Pca (1 paper, 2017). "Nonsense and missense mutations of MSR1 were identified to be associated with increased Pca risk." (PMID 29137340, 2017). "A higher level of MSR1 density was associated with lower clinical stage, positive lymph nodes, smaller tumour size, and lower preoperative PSA level and good prognosis of Pca." (PMID 29137340, 2017).
preeclampsia (1 paper, 2021). Preeclampsia is a hypertensive disorder of pregnancy that is characterized by new-onset hypertension with proteinuria presenting after 20 weeks of gestation, and depending on mild or severe forms may initially present with severe headache, visual disturbances, and hyperreflexia. "M2 macrophages (CD136+MRC1+C1QA+C1QB+, P=0.007) and mast cells (TPSAB1, P=0.007) were decreased in early-onset preeclampsia samples, while M1 macrophages (CD86+MSR1+) were not altered based on gene expression." (PMID 34992598, 2021).
schizophrenia (1 paper, 2021). A major psychotic disorder characterized by abnormalities in the perception or expression of reality. "Variants in the MSR1-encoding gene have been nominally significantly associated in a schizophrenia GWAS38, and have been robustly associated with AD39 and PD38." (PMID 34857772, 2021). "Here, we observe a causal association between decreased MSR1 expression and increased risk of schizophrenia, suggesting a protective role." (PMID 34857772, 2021). "We find that a cis-pQTL (rs150158578) associated with decreased serum MSR1 (macrophage scavenger receptor types I and II) is causal for schizophrenia, supported by evidence from colocalisation analysis (CLPP4 = 0.75) and two-sample MR (BETA = −0.2205; SE = 0.0522; Wald ratio Padj = 1.44 × 10−2)." (PMID 34857772, 2021).
skin changes (1 paper, 2024). "The gene sets encompass numerous genes previously implicated in the pathogenesis of SSc, such as Acta2, Col1a1, Col3a1, Smad3, Ctgf, Msr1, Cd4, Cd8a and Cd68, supporting the potential of anti-PRMT5 in induction of SSc-like skin changes." (PMID 38684324, 2024).
squamous cell lung carcinoma (1 paper, 2021). A carcinoma arising from squamous bronchial epithelial cells. "Similarly, miR-579-3p has been reported to regulate the development of squamous cell lung carcinoma by targeting macrophage scavenger receptor 1 (MSR1)." (PMID 34288804, 2021).
staphylococcal pneumonia (1 paper, 2012). Pneumonia caused by infections with bacteria of the genus staphylococcus, usually with staphylococcus aureus. "Mice with deletions of MSR1 or CD36 have increased susceptibility to pneumococcal or staphylococcal pneumonia." (PMID 22396727, 2012).
tuberculosis (1 paper, 2013). A chronic, recurrent infection caused by the bacterium Mycobacterium tuberculosis. "No SNPs within the gene encoding or within 1 kb of the promoter sequence of MSR1 were associated with either susceptibility or resistance to tuberculosis." (PMID 23617307, 2013). "We studied the frequencies of 25 polymorphisms of MSR1 (SRA) and 22 in MARCO in individuals with tuberculosis (n=1284) and matched controls (n=1349)." (PMID 23617307, 2013). "None of the SNPs genotyped in MSR1 were associated with tuberculosis susceptibility." (PMID 23617307, 2013).
tumor (264 papers, 2009 to 2026). "Our findings suggest that tumor-infiltrating MSR1/CD204 is a biomarker that is associated with the prognosis of ccRCC." (PMID 38370385, 2024). "This was in line with previous publications that reported the presence of MSR1 in tumor-associated macrophages (TAM) and correlated that presence with detrimental prognoses for several tumor types." (PMID 38612803, 2024). "Nevertheless, M2 markers, including Cd163, Msr1, and Fcgr1, were highly expressed in Marco4 and Marco6, suggesting their association with tumor progression." (PMID 37697332, 2023). "The tumour promoting effect of loss of MSR1 was determined to be a result of activation of the PI3K-AKT-GSK3β pathway and increased expression of β-Catenin." (PMID 36325338, 2022). "Mutations in MSR1 are the second most frequent genetic alteration, which represent 3.3% (1250 out of 38170 tumour samples) according to the COSMIC (the Catalogue Of Somatic Mutations In Cancer) database." (PMID 36325338, 2022). "Whilst deletion of MSR1 and the surrounding chromosome region in tumour cells has been associated with poor cancer prognosis, the expression of MSR1 in tumour cells is ultimately low." (PMID 36325338, 2022). "Recent studies have shown that MSR1 is highly expressed in M2‐like pre‐tumor macrophages, which are associated with tumorigenesis and development, such as angiogenesis and immunosuppressive factor production." (PMID 35142109, 2022). "The class A macrophage scavenger receptor (MSR1 or CD204 gene) is expressed by tumor-associated M2 macrophages that induce tumor progression and angiogenesis by suppressing immunity in the tumor microenvironment ⁠." (PMID 33059718, 2020). "Lipid accumulation in tumor-associated DCs, mediated by upregulation of scavenger receptor A (SR-A1 or MSR1), negatively regulates their capacity to process antigen via MHC class II and to stimulate allogenic T cells." (PMID 32823961, 2020). "Moreover, the positive correlation between MSR1 levels and StromalScore further supported the potential role of MSR1 in the formation and maintenance of the tumor microenvironment, particularly with components associated with the tumor stroma." (PMID 39502334, 2024). "Furthermore, tumours with MSR1 mutations increased sensitivity to treatment with the AKT inhibitor GSK690693, according to the Genomics of Drug Sensitivity in Cancer (GDSC) project using the Pan-cancer database." (PMID 36325338, 2022). "In addition to altered T cells, the ICC/IDC TME was associated with elevated macrophage expression of CD163 and MSR1, markers of pro-tumor M2 macrophages." (PMID 36229464, 2022). "MSR1 has been implicated in tumour development and progression, and tumour‐associated macrophages (TAMs) have been shown to resemble M2 macrophage phenotype with MSR1 protein expression." (PMID 31028084, 2019). "MSR1 has in recent years been established as a good marker for TAMs which resemble rather a M2 alternatively activated phenotype and have been associated with tumour promotion." (PMID 31028084, 2019). "A meta-analysis was performed to evaluate the prognostic value of tumor associated macrophages and macrophage scavenger receptor 1, marker for a subset of macrophages, by pooled hazard ratio and 95% confidence intervals from qualified studies following a systemic search." (PMID 29137340, 2017). "Given that aberrant kallikrein gene expression is key to the pathogenesis in many tumours, we predict that MSR1 CNVs might underlie increased susceptibility to cancer in these patients." (PMID 26781568, 2016). "Moreover, MSR1 is expressed by M2-type tumor-associated macrophages and may thereby promote tumorigenesis." (PMID 34281234, 2021). "To gain further insights into the role of MSR1 in tumor immune responses, we employed the CIBERSORT method to elucidate the immune modulation of MSR1 in THCA." (PMID 39502334, 2024).